AXIN1 (axin 1)
Diseases named in the same sentence as AXIN1 in open-access papers (continued):
Sharing a sentence is not in itself a finding about the gene and the disease.
dyslipidemia (2 papers, 2016 to 2025). "This suggests a potential regulatory role for AXIN1 in adipocyte differentiation, warranting further exploration to elucidate its specific contributions to metabolic syndrome-related processes and obesity." (PMID 40076884, 2025). "Notably, AXIN1, a key component of the β-catenin destruction complex, may play a crucial role in regulating adipocyte differentiation, suggesting potential contributions to metabolic syndrome and obesity that remain largely unexplored." (PMID 40076884, 2025).
esophageal squamous cell carcinoma (2 papers, 2019 to 2025). Esophageal squamous cell carcinoma (ESCC) is a type of esophageal carcinoma (EC) that can affect any part of the esophagus, but is usually located in the upper or middle third. "A correlation between reduced AXIN1 expression and tumor progression has been reported in esophageal squamous cell carcinoma, and several mutations and polymorphisms of AXIN1 have been found in squamous cell tumors and cell lines." (PMID 31143301, 2019).
inflammatory bowel disease (2 papers, 2022 to 2023). A spectrum of small and large bowel inflammatory diseases of unknown etiology. "A recent study found elevated AXIN1 levels in inflammatory bowel disease but not in IBS." (PMID 35565656, 2022).
lymphoma (2 papers, 2021 to 2022). A malignant (clonal) proliferation of B- lymphocytes or T- lymphocytes which involves the lymph nodes, bone marrow and/or extranodal sites. "A recent study has shown that the ubiquitination of Axin1 by TRIM11 was involved in the carcinogenesis of lymphoma." (PMID 35237324, 2022). "In contrast to our results in the different lymphoma cell types, we found that AXIN1, AXIN2 and WIF1 mRNA levels were elevated in transformed breast epithelial cells." (PMID 33462997, 2021).
meningioma (2 papers, 2016 to 2020). A generally slow growing tumor attached to the dura mater. "Microsatellite markers specific for two different Wnt genes that were used (CDH1, AXIN1), revealed a fraction of meningiomas with MSI." (PMID 27429002, 2016).
osteoarthritis (2 papers, 2024 to 2025). A noninflammatory degenerative joint disease occurring chiefly in older persons, characterized by degeneration of the articular cartilage, hypertrophy of bone at the margins and changes in the synovial membrane. "Additionally, specific deletion of AXIN1 in condylar chondrocytes resulted in an osteoarthritis-like phenotype in the temporomandibular joint, a degenerative disease characterized by pathological condylar cartilage degeneration in adults." (PMID 38291457, 2024). "This led to AXIN1 accumulation, thereby activating WNT/β-catenin signaling and promoting the progression of osteoarthritis (OA)." (PMID 38291457, 2024). "The remaining markers, including AXIN1, SIRT, and especially ST1A1, have been suggested to have protective effects against osteoarthritis and may serve as potential biomarkers for pain." (PMID 41020650, 2025).
Salmonella Infections (2 papers, 2012 to 2016). Infections with bacteria of the genus SALMONELLA. "Both TRAP1 and AXIN 1, the two putative candidate genes on chromosome 14 for Campylobacter colonisation resistance, have been also associated with Salmonella infection in previous studies." (PMID 27090510, 2016). "We found that the levels of Axin1 ΔRGS domain mutant were significantly reduced after Salmonella infection." (PMID 22509369, 2012). "Taken together, these data showed that increased ubiquitination, SUMOylation, and proteasome degradation of Axin1 occurs during Salmonella infection." (PMID 22509369, 2012). "We also tested the other Axin1 mutations; however, the protein levels of these Axin1 mutants did not change after Salmonella infection." (PMID 22509369, 2012). "Postpathogenic Salmonella infection, Axin1 was scattered as dots in the cytoplasm." (PMID 22509369, 2012). "The reduction of Axin1 occurred at an early stage of Salmonella infection." (PMID 22509369, 2012). "In addition, the Axin1 ΔRGS ΔDIX double mutation lost the target domain, and its protein level was not reduced by Salmonella infection." (PMID 22509369, 2012). "Moreover, IP data indicated that there was no change in Axin SUMOylation after Salmonella infection in cells transfected with Axin1 ΔDIX." (PMID 22509369, 2012). "Additionally, the Axin1 mRNA level was not changed by Salmonella infection in vivo." (PMID 22509369, 2012).
adenosarcoma (1 paper, 2017). A low grade malignant neoplasm characterized by the presence of a benign epithelial component (tubular and cleft-like glands) and a low grade sarcomatous component that contains varying amounts of fibrous and smooth muscle tissues. "In addition, the Wnt signaling pathway was significantly altered in adenosarcomas, which harbored, among other alterations in Wnt pathway‐related genes, homozygous deletions of APC (1/19, 5%) and SMARCA4 (1/19, 5%) and nonsynonymous mutations affecting AXIN1 (1/19, 5%) and AXIN2 (1/19, 5%)." (PMID 28267263, 2017).
adenovirus infection (1 paper, 2011). "The results obtained by Axin-1-adenovirus infection suggested that Wnt/β-catenin signaling is required for regeneration of a complete limb in adulthood." (PMID 21814549, 2011).
Anxiety (1 paper, 2023). Intense feelings of nervousness, tension, or panic often arise in response to interpersonal stresses. "Among their top 10 most significant proteins that were altered after treatment were the same proteins that we found in our OPLS and OPLS-DA models for depression and anxiety (CXCL6, STAMPB, CXCL1, SIRT2, AXIN1, CXCL5, ST1A1, and IL-7)." (PMID 36979692, 2023).
brain injury (1 paper, 2017). Acute and chronic (see also brain INJURIES, CHRONIC) injuries to the brain, including the cerebral hemispheres, CEREBELLUM, and brain STEM. "We conclude that CST5, AXIN1 and TRAIL are worthy of further study in the context of a pre-hospital or pitch-side test to detect brain injury." (PMID 28694499, 2017).
cardiac hypertrophy (1 paper, 2021). "Collectively, our findings have thus explored a novel pathophysiological role for miR-128 in the stimulation of cardiac hypertrophy and heart failure via direct blemish on the inhibitory activity of Axin1 against Wnt1/β-catenin signaling." (PMID 34965835, 2021). "Our study provides evidence indicating miR-128 as an inducer of HF and cardiac hypertrophy by enhancing Wnt1/β-catenin in an Axin1-dependent nature." (PMID 34965835, 2021).
cerebrovascular disease (1 paper, 2020). "Based on human and mouse phenotype ontologies, DVL1 and AXIN1 were annotated to the “cerebrovascular disease” term and, in particular, with AVM and telangiectasia phenotypes." (PMID 32560555, 2020).
colorectal tumor (1 paper, 2024). "In the mouse xenografts model, treatment with CK1δ/ε inhibitor SR3029 and knockdown of SIAH1 resulted in attenuated colorectal tumor growth via stabilizing AXIN1." (PMID 38419282, 2024).
congenital heart defects (1 paper, 2020). "This study aimed to investigate possible associations of the susceptibility to congenital heart defects (CHDs) with AXIN1 rs1805105, rs12921862 and rs370681 gene variants and haplotypes, and AXIN2 rs2240308 gene variant." (PMID 33096676, 2020). "The present study is an exploratory research that reveals significant positive associations between susceptibility to congenital heart defects and AXIN1 rs1805105, rs12921862 and rs370681 (C-C-C and C-C-T) haplotypes and AXIN2 rs2240308 variant." (PMID 33096676, 2020).
Crohn disease (1 paper, 2023). A gastrointestinal disorder characterized by chronic inflammation involving all layers of the intestinal wall, noncaseating granulomas affecting the intestinal wall and regional lymph nodes, and transmural fibrosis. "Our paper reported increased Axin1 expression at both the mRNA and protein levels in human IBD, including ulcerative colitis (UC), and Crohn’s disease (CD)." (PMID 38010886, 2023).
GEJ adenocarcinomas (1 paper, 2004). "The frequent nuclear localisation of β-catenin in GEJ adenocarcinomas cannot be attributed by AXIN1 gene mutations." (PMID 14970870, 2004). "Since mutations in APC, β-catenin and AXIN1 do not play a major role in the frequent TCF/β-catenin activation in GEJ adenocarcinomas, other components should be considered." (PMID 14970870, 2004). "In addition, the role of the frequent LOH of the AXIN1 locus in GEJ adenocarcinomas deserves further investigation." (PMID 14970870, 2004). "We found a G2063A allele frequency of 4 and 3% in GEJ adenocarcinoma patients and healthy controls, respectively, indicating that this AXIN1 gene variant is an SNP and not a mutation." (PMID 14970870, 2004). "In 17 GEJ adenocarcinoma samples, no AXIN1 gene mutations were found." (PMID 14970870, 2004). "Our immunohistochemical results indicate that AXIN1 gene silencing does not occur in GEJ adenocarcinomas." (PMID 14970870, 2004).
germ cell tumor (1 paper, 2022). A benign or malignant, gonadal or extragonadal neoplasm that originates from germ cells. "It is biologically plausible that several genes have pleiotropic effects on both male and female fertility traits, for instance, the AXIN1 is requested for successful embryo development and has been shown to act as a suppressor of testicular germ cell tumors." (PMID 35692843, 2022).
glioblastoma (1 paper, 2019). The most malignant astrocytic tumor (WHO grade IV). "In glioblastoma inhibition of MCAF1 resulted in reduced wnt signaling mediators Axin1 and β-catenin." (PMID 31546954, 2019).
HCMV infection (1 paper, 2015). "HCMV infection is characterized by an increase in Axin1 expression followed by degradation of β-catenin, while infection with HSV1 or HSV2 does not result in β-catenin degradation." (PMID 26729153, 2015). "The accumulation of TNKS during HCMV infection and resulting Axin1 stabilization and decrease in β-catenin expression is a unique feature of HCMV infection." (PMID 26729153, 2015). "Similarly, the involvement of APC and casein kinase 1 (CKI) in HCMV-mediated Wnt modulation remains to be explored, and might still play a significant role in regulating Axin1 stability and degradation during HCMV infection." (PMID 26729153, 2015). "HCMV infection of human foreskin fibroblasts induced Axin1, the negative regulator of Wnt, resulting in decreased expression of β-catenin." (PMID 26729153, 2015). "However, TNKS-mediated regulation may not be the only mechanism leading to Axin1 stabilization in HCMV infection." (PMID 26729153, 2015).
heart failure (1 paper, 2021). Inability of the heart to pump blood at an adequate rate to meet tissue metabolic requirements. "Not surprisingly, downregulation of miR-128 in Axin1 deficient cardiomyocytes had bare effect on reduction of Wnt1/β-catenin, suggesting miR-128 upregulates Wnt1/β-catenin activation and its driven heart failure progression in a Axin1-dependent manner." (PMID 34965835, 2021). "We demonstrate miR-128 and Wnt1/β-catenin are synergistically activated in heart failure, and blockade of miR-128 downregulates Wnt1/β-catenin coupled with reinforced Axin1 expression, leading to ameliorated heart dysfunction." (PMID 34965835, 2021). "Together, these data decisively demonstrated miR-128 mediates the progression of heart failure and the enhancement of Wnt1/β-catenin pathway by downregulatory target on Axin1." (PMID 34965835, 2021).
HIV-1 infection (1 paper, 2020). The type species of lentivirus and the etiologic agent of acquired immunodeficiency syndrome (AIDS). "Random forest analysis was performed to pin-point proteins discriminating between groups; five proteins (STAMBP, CD5, TFG-α, TRANCE, AXIN1) were the strongest prediction factors for treated HIV-1 infection." (PMID 32906648, 2020). "It would be important to conduct studies specifically addressing the role of AXIN1 in osteoclast apoptosis during treated HIV-1 infection in children." (PMID 32906648, 2020). "An additional molecule, AXIN1, among the five associated with the HIV-1 status in our analyses may have relevance for bone dysfunctions in HIV-1 infection." (PMID 32906648, 2020).
Hyperinsulinemia (1 paper, 2023). An increased concentration of insulin in the blood. "HbA1c correlated positively with changes of MCP-2 and IL-15-RA during hyperinsulinemia (Rho ≥ 0.51) and inversely with changes of CXCL1, MMP-1 and Axin-1 during hypoglycemia (Rho ≤ -0.55)." (PMID 37400734, 2023).
intestinal tumors (1 paper, 2026). "In line with our findings, optimal Wnt signaling levels for HCC formation were estimated to be lower than those required for intestinal tumors, further supporting the view that AXIN1 mutations facilitate “just-right” levels of Wnt signaling to enable HCC development." (PMID 41550750, 2026).
invasive ductal carcinomas (1 paper, 2016). "We further analysed the association between AXIN1 and RUNX1 at the protein level using a commercial tumour microarray, TMA-1007, which included among others duplicate cores from 31 ER+ invasive ductal carcinomas in which ER was expressed at either low (ERlow) or high levels (ERhigh)." (PMID 26916619, 2016).
metastatic tumors (1 paper, 2025). "To assess the clinical relevance of Ephexin1 alongside β-catenin and Axin1 in human CRC, we examined tissue microarrays of colorectal tissues, including normal tissues, carcinomas of varying grades, and metastatic tumors." (PMID 39741188, 2025).
papillary thyroid carcinoma (1 paper, 2023). "Association of AXIN1 rs1805105 polymorphism with clinical characteristics of papillary thyroid carcinoma." (PMID 36510340, 2023).
polycystic kidney disease (1 paper, 2015). A usually autosomal dominant and less frequently autosomal recessive genetic disorder characterized by the presence of numerous cysts in the kidneys leading to end-stage renal failure. "NEK1 and CTNNB1, together with AXIN1, GSK3B and TSC2, participate in the Wnt signaling pathway in urological cancer cells and polycystic kidney disease (PKD)." (PMID 26317783, 2015).
pulmonary hypertensive (1 paper, 2011). "Expression of Wnt ligands (Wnt1, Wnt3a, and Wnt5a) and Wnt signaling upstream regulator genes (Frizzled1 and 2 receptors and sFRP-1) and intracellular effectors (Axin1 and GSK3β) were investigated in pulmonary hypertensive rat lungs, 3 and 5 weeks after MCT injury." (PMID 21533110, 2011).
rectal tumors (1 paper, 2025). "AXIN1 and APC co-mutations demonstrated location-specific enrichment between colon and rectal tumors." (PMID 40860720, 2025).
respiratory infection (1 paper, 2025). "These similar findings of both pregnancy and childhood levels suggest a protective effect of the AXIN1 protein levels against risk of early childhood respiratory infections." (PMID 40595623, 2025). "Interestingly, similar results showing a decreased risk of respiratory infections from higher AXIN1 levels at age 1 year in the EMIL cohort were demonstrated, supporting the findings from COPSAC2010." (PMID 40595623, 2025). "In addition, our findings suggest that the AXIN1 protein, which was modified by air pollution exposure to play a role in the downregulation of infection proneness in young children and could potentially serve as a target protein in respiratory infection prevention." (PMID 40595623, 2025).
Sepsis (1 paper, 2024). Sepsis is defined as life-threatening organ dysfunction caused by a dysregulated host response to infection. "AXIN-1, a component of the β-catenin degradation complex, regulates the Wnt signaling pathway, which recent studies have linked to sepsis." (PMID 39205680, 2024). "Our study indicates that the association of piperine with reduced sepsis risk is partly due to AXIN-1, accounting for approximately 16.296% of this protective effect." (PMID 39205680, 2024). "The association of Piperine with increased AXIN1 correlated with a reduced sepsis risk, contributing 16.296% to Piperine’s protective effect." (PMID 39205680, 2024). "Piperine, in particular, demonstrated a protective effect against sepsis, mediated through its interaction with AXIN1, contributing to a 16.296% reduction in sepsis risk." (PMID 39205680, 2024). "Piperine’s protective effect was mediated through its interaction with AXIN1, contributing to a 16.296% reduction in sepsis risk." (PMID 39205680, 2024). "The association of X-19438 with increased AXIN1 correlated with a reduced sepsis risk, contributing 12.380% to the protective effect of X-19438." (PMID 39205680, 2024). "The detailed mechanism by which piperine reduces sepsis risk via AXIN1 warrants further investigation." (PMID 39205680, 2024). "We identified 36 metabolites significantly associated with sepsis (p < 0.05), with AXIN1, FGF-19, FGF-23, IL-4, and OSM showing an inverse association, suggesting a protective role, while IL-2 exhibited a positive correlation, indicating a potential risk factor." (PMID 39205680, 2024). "This suggests a potential pathway where Piperine influences sepsis outcomes by modulating AXIN1 levels." (PMID 39205680, 2024). "In our study, we identified several inflammatory factors, including FGF-19, AXIN1, FGF-23, IL-4, OSM, and IL-2, that showed statistically significant associations with sepsis risk using the IVW method in MR analyses." (PMID 39205680, 2024). "In our study, X-19438 was found to inhibit the occurrence of sepsis through a positive correlation with AXIN1." (PMID 39205680, 2024). "Experimental validation confirmed significantly elevated IL-2 levels and reduced FGF-19, AXIN1, piperine, and 9-hydroxyoctadecanoic acid levels in sepsis patients compared to healthy controls." (PMID 39205680, 2024). "Inflammatory factors such as AXIN-1, FGF-19, FGF-23, IL-4, and OSM were negatively causally associated with sepsis, while IL-2 was positively associated." (PMID 39205680, 2024). "In our MR analysis, we discovered that piperine influences sepsis progression by affecting AXIN1." (PMID 39205680, 2024). "The results showed that sepsis patients exhibited significantly elevated levels of the inflammatory factor IL-2 and significantly reduced levels of FGF-19 and AXIN1 compared to healthy controls." (PMID 39205680, 2024). "The significant correlations observed between piperine and AXIN1, as well as 9-hydroxyoctadecanoic acid and IL-2 and FGF-19, further support the intricate relationships between metabolites and inflammatory factors in the context of sepsis." (PMID 39205680, 2024). "Similar negative associations were observed for AXIN1 (OR = 0.715, CI = 0.517–0.990), FGF-23 (OR = 0.783, CI = 0.624–0.981), IL-4 (OR = 0.772, CI = 0.608–0.980), and OSM (OR = 0.755, CI = 0.592–0.962), whereas IL-2 showed a positive correlation with sepsis (OR = 1.320, CI = 1.008–1.729)." (PMID 39205680, 2024).
teratoma (1 paper, 2024). A non-seminomatous germ cell tumor characterized by the presence of various tissues which correspond to the different germinal layers (endoderm, mesoderm, and ectoderm). "The patient with MSO also harboured a novel germline AXIN1 variant, presenting a loss of heterozygosity in its benign and malignant teratoma tissues and observable β-catenin cytoplasmic accumulation." (PMID 38396644, 2024). "Notably, the LOH for AXIN1 was detected in both benign and malignant (MSO) teratoma tissues from this patient, contrarily to its eutopic thyroid tissues." (PMID 38396644, 2024).
thyroid (1 paper, 2022). "Molecular alterations in the Wnt/β-catenin signaling pathway involved in adenomatous polyposis coli (APC), axis inhibition protein 1 (AXIN1), and catenin beta 1 (CTNNB1) contribute to thyroid tumorigenesis." (PMID 36157447, 2022).
type 2 diabetes (1 paper, 2016). "From these evidences, we could make hypothesis that type 2 diabetes is caused by a decrement of glucose import because activation of CTNNB1 is inhibited by lower expression of AXIN1." (PMID 27490120, 2016).